SH3D19 (SH3 domain containing 19)
Description:
May play a role in regulating A disintegrin and metalloproteases (ADAMs) in the signaling of EGFR-ligand shedding. May be involved in suppression of Ras-induced cellular transformation and Ras-mediated activation of ELK1. Required for regulation of cell morphology and cytoskeletal organization.
Synonyms: EBP; DKFZp434D0215; EVE1; Kryn; SH3P19; Eve-1
Tractability: Antibody: its Gene Ontology location is reachable by antibodies, with high confidence. PROTAC: ubiquitination databases record sites on it.
Gene: Protein-coding gene on chromosome 4 (151,102,751 to 151,409,365, reverse strand). Ensembl gene ENSG00000109686.
Subcellular location: Cytoplasm; Nucleus
Subcellular location (Human Protein Atlas): Cytosol; Nucleoplasm
Pathways (Reactome):
Vesicle-mediated transport: Golgi Associated Vesicle Biogenesis
Gene Ontology:
Molecular function: protein binding; protein-macromolecule adaptor activity
Biological process: positive regulation of membrane protein ectodomain proteolysis; cytoskeleton organization
Cellular component: cytosol; nucleoplasm; plasma membrane; cytoplasm; nucleus
Genetic constraint (gnomAD): Loss-of-function variants: 36 observed, 75.63 expected, observed/expected ratio (o/e) 0.48, 90% interval 0.36 to 0.63. The upper end of that interval is the gene's LOEUF score, 0.63, which puts it in group 2 of 6, group 1 being the genes least tolerant of losing a copy. Missense variants: 891 observed, 1,021.6 expected, observed/expected ratio (o/e) 0.87, 90% interval 0.82 to 0.92. Synonymous variants: 338 observed, 379.71 expected, observed/expected ratio (o/e) 0.89, 90% interval 0.81 to 0.97.
Homologues: Orthologues: chimpanzee SH3D19 (99% identical), macaque SH3D19 (97% identical), rabbit SH3D19 (85% identical), dog SH3D19 (84% identical), pig SH3D19 (83% identical), mouse Sh3d19 (79% identical), rat Sh3d19 (78% identical), guinea pig SH3D19 (60% identical), tropical clawed frog sh3d19 (49% identical), zebrafish sh3d19 (30% identical), Caenorhabditis elegans sorb-1 (14% identical), Caenorhabditis elegans B0303.7 (9% identical), and 3 more. Paralogues in human: SORBS2 (16% identical), SORBS1 (14% identical), SORBS3 (10% identical), SH3RF3 (9% identical), SH3RF1 (8% identical), SH3RF2 (7% identical), SH3GL1 (7% identical), SH3GL2 (7% identical), SH3GL3 (7% identical), NCF4 (6% identical), SH3GLB1 (6% identical), SH3GLB2 (6% identical).
Diseases named in the same sentence as SH3D19 in open-access papers:
SH3D19 is named in the same sentence as 9 diseases in open-access papers, as found by Europe PMC text mining. Sharing a sentence is not in itself a finding about the gene and the disease. The quoted sentences say what the papers report.
acute myeloid leukaemia (1 paper, 2015). "SH3D19 codes for the tumour suppressor EBP that inhibits ras driven transformation in acute myeloid leukaemia." (PMID 25807374, 2015).
bronchiolitis (1 paper, 2024). Inflammation of the bronchioles characterized by swelling of the bronchioles and mucus accumulation. "A variant in SH3D19 showed borderline-significant association with overall bronchiolitis." (PMID 39299705, 2024).
viral infections (1 paper, 2021). "The serine protease 48 (PRSS48) and SH3 domain-containing 19 (SH3D19) genes do not have known functions relating to viral infections or respiratory illness." (PMID 34409086, 2021).
SH3D19 also shares sentences with these, for which no sentence is quoted: infection (2 papers); essential hypertension (1); major depression (1); Myelodysplasia (1); neuromuscular disease (1); tumour (1).